DEFA4 (defensin alpha 4)
Description:
Host-defense peptide that has antimicrobial activity against Gram-negative bacteria, and to a lesser extent also against Gram-positive bacteria and fungi. Exhibits antimicrobial activity against Gram-negative E.coli and E.aerogenes and Gram-positive S.faecalis, S.aureus and B.cereus and the yeast C.albicans (in vitro). Interacts with pathogenic surface proteins and toxins, such as HIV-1 surface protein gp120 and B.anthracis anthrax lethal factor lef. Protects blood cells against infection with HIV-1 (in vitro). Inhibits enzymatic activity of B.anthracis lef/anthrax lethal factor (in vitro). Inhibits corticotropin (ACTH)-stimulated corticosterone production (in vitro).
Synonyms: HP-4; DEF4; HNP-4; HP4
Tractability: Antibody: its Gene Ontology location is reachable by antibodies, with high confidence; UniProt places it where antibodies can reach, with medium confidence; UniProt predicts a signal peptide or a membrane-spanning region.
Gene: Protein-coding gene on chromosome 8 (6,935,820 to 6,938,306, reverse strand). Ensembl gene ENSG00000164821.
Subcellular location: Secreted; Cytoplasmic vesicle, secretory vesicle
Pathways (Reactome):
Immune System: Alpha-defensins; Defensins; Neutrophil degranulation
Gene Ontology:
Molecular function: protein homodimerization activity; pore-forming activity
Biological process: antibacterial humoral response; antifungal humoral response; antimicrobial humoral immune response mediated by antimicrobial peptide; antimicrobial humoral response; defense response to fungus; defense response to Gram-negative bacterium; defense response to Gram-positive bacterium; innate immune response; disruption of plasma membrane integrity in another organism; defense response
Cellular component: azurophil granule; extracellular region; Golgi lumen; specific granule lumen; transport vesicle
Genetic constraint (gnomAD): Loss-of-function variants: 9 observed, 5.13 expected, observed/expected ratio (o/e) 1.75, 90% interval 0.96 to 1.95. That is too few expected variants to judge how well the gene tolerates losing a copy. Missense variants: 216 observed, 132.17 expected, observed/expected ratio (o/e) 1.63, 90% interval 1.46 to 1.83. Synonymous variants: 77 observed, 48.45 expected, observed/expected ratio (o/e) 1.59, 90% interval 1.32 to 1.89.
Homologues: Orthologues: chimpanzee DEFA4 (99% identical), rabbit MCP-1 (43% identical), rat Defa5 (43% identical), rat Np4 (43% identical), rat Defa31 (41% identical), mouse Defa23 (39% identical), mouse Defa31 (39% identical), mouse Defa17 (38% identical), mouse Defa3 (38% identical), mouse Defa34 (38% identical), rat Defa9 (38% identical), rat RatNP-3b (38% identical), and 29 more. Paralogues in human: DEFA5 (48% identical), DEFA6 (48% identical), DEFA1 (44% identical), DEFA1B (44% identical), DEFA3 (44% identical).
Diseases named in the same sentence as DEFA4 in open-access papers:
DEFA4 is named in the same sentence as 36 diseases in open-access papers, as found by Europe PMC text mining. Sharing a sentence is not in itself a finding about the gene and the disease. The quoted sentences say what the papers report.
COVID-19 (7 papers, 2021 to 2025). A disease caused by infection with severe acute respiratory syndrome coronavirus 2. "Single cell RNA sequencing analyses showed the increased presence of dysfunctional neutrophils expressing S100A8, S100A9, DEFA3 and DEFA4 genes in the PBMCs of severe COVID-19 patients suggesting association of the phenotypic alterations in neutrophils with disease severity." (PMID 34746027, 2021). "Up-regulation of DEFA4 and neutrophil-related genes in patients with COVID-19 indicated an increased number of neutrophils and degranulation." (PMID 35668817, 2022). "The elevated level of DEFA4 expression was correlated with the status and severity of symptoms in COVID-19 patients." (PMID 35668817, 2022). "For instance, while reducing the correlation between DEGs including IL10, CXCL8, NFKB1, ARG1, and SOD2, new strong associations appeared between ELANE, DEFA4, AZU1, CTSG, and LCN2, with an overall tendency to higher relationships amid neutrophil-mediated immunity genes in COVID-19 patients." (PMID 35269470, 2022). "Furthermore, up-regulation of DEFA4 and neutrophil-related genes may reflect emergency myelopoiesis in fatal COVID-19." (PMID 35668817, 2022). "The COVID-19 dataset revealed CAMP (AUC: 0.692), LTF (AUC: 0.764), DEFA1B (AUC: 0.701), SAMD9(AUC: 0.786), GBP1(AUC: 0.757), DDX60 (AUC: 0.802), DEFA4 (AUC: 0.763), and OAS3(AUC: 0.801) that exhibited superior diagnostic capabilities." (PMID 38115996, 2023).
viral infection (6 papers, 2017 to 2025). "Several genes in this group (CTSG, encoding the neutrophil serin protease Cathepsin G; DEAFA4, defensin alpha 4; LCN2, lipocalin 2; OLFM4, BPI and CD24), are known to be overexpressed in patients with severe viral infections, including COVID-197,14." (PMID 35181735, 2022). "Together, this network reveals the relevant biology of DEFA4 as a biomarker for bacterial vs. viral infection as well as for severity." (PMID 34442377, 2021). "Among the 6 genes, over-expressed genes (HK3, DEFA4, BATF) were positively correlated with severity of viral infection, and under-expressed genes (HLA-DPB1, LY86, TGFBI) were negatively correlated with severity." (PMID 35042868, 2022). "Each of the 6 genes were significantly differentially expressed between patients with viral infections who survived and those who did not, of which 3 genes (DEFA4, BATF, HK3) were higher and 3 genes (TGFBI, LY86, HLA-DPB1) were lower in those who died." (PMID 35042868, 2022). "Several differentially expressed genes between the two trajectories (CTSG, PRC1, DEFA4, KIF15, TCEAL9, HMMR, CEP55, and AZU1) were overexpressed in patients with severe viral infection, but not in those with non-severe viral infection compared to HCs." (PMID 33765435, 2021).
influenza (4 papers, 2021 to 2024). An acute viral infection of the respiratory tract, occurring in isolated cases, in epidemics, or in pandemics; it is caused by serologically different strains of viruses (influenzaviruses) designated A, B, and C, has a 3-day incubation period, and usually lasts for 3 to 10 days. "Our integrated analysis and validation results also again illustrate that these candidate genes, including ELANE, DEFA4, involved in NETs formation, could cause or participate in the process of severe influenza." (PMID 33448094, 2021). "Moreover, DEFA4 also may serve as a biomarker for clinical diagnosis and as a target for treatment of severe influenza infection." (PMID 36650470, 2023). "In comparison, three patients had high activation of only a subset of influenza-connected genes PRTN3, LTF, PGLYRP1, DEFA1B, DEFA1, DEFA4, ELANE, and MPO." (PMID 34335605, 2021).
Sepsis (4 papers, 2022 to 2025). Sepsis is defined as life-threatening organ dysfunction caused by a dysregulated host response to infection. "Prior time series analysis of septic patients identified three genes in the elastase family (ELANE, CTSG, PRTN3) and DEFA4 as candidate biomarkers for sepsis, while other studies likewise implicated NETosis genes including ALPL." (PMID 41385588, 2025). "A similar approach to the present study was used to build a seven gene expression model, including DEFA4, that predicted sepsis severity with reasonable accuracy (ROC = 0.88)." (PMID 41385588, 2025). "In the end, we managed to formulate a signature of 7 IRGs for the prognosis of sepsis patients: − 0.465 × CCL5 + 0.215 × DEFA4 − 1.487 × NFYC + 1.055 × ESR1 − 0.737 × TNFRSF8 − 0.228 × CX3CR1 + 1.003 × SERPINA3." (PMID 36650470, 2023). "Among these 7 IRGs, which could predict the prognosis of sepsis patients, CCL5, DEFA4, ESR1 and CX3CR1 were broadly researched in previous studies." (PMID 36650470, 2023). "Therefore, DEFA4, ELANE, MPO, and TFRC might be related to immune paralysis in sepsis." (PMID 36532037, 2022).
asthma (3 papers, 2022 to 2025). "It was found that DEFA4 was significantly associated with the severity of asthma." (PMID 35668817, 2022). "Most DEGs of this term, including DEFA3, DEFA4, ELANE, and LTF, encode antimicrobial peptides in neutrophils, indicating that the upregulated antimicrobial immune response in the AR-asthma group is mainly mediated by neutrophils." (PMID 36569909, 2022). "Among 19 up-regulated genes, DEFA4 was remarkably present in the neutrophil-predominant asthma phenotype compared to other asthma subtypes." (PMID 35668817, 2022). "Obviously, DEFA4 has a significant influence on respiratory-related diseases such as asthma and idiopathic pulmonary fibrosis (IPF)." (PMID 35668817, 2022). "Furthermore, DEFA4 also plays a significant role in the respiratory system, and it is upregulated in various respiratory-related disorders, such as asthma and idiopathic pulmonary fibrosis (IPF)." (PMID 40333951, 2025).
autoimmune disease (3 papers, 2014 to 2025). A disorder resulting from loss of function or tissue destruction of an organ or multiple organs, arising from humoral or cellular immune responses of the individual to their own tissue constituents. "Interestingly, the three genes (LTF, CAMP, and DEFA4, encoding lactoferrin, cathelicidin, and α-defensin 4) were closely related to immune function and autoimmune diseases." (PMID 24741625, 2014). "Numerous studies have demonstrated that DEFA4 plays a crucial role not only in anti-microbial activity and antiviral activity, but also in infectious diseases, and autoimmune diseases." (PMID 40333951, 2025). "Furthermore, DEFA4 exhibits pro-inflammatory activity in the intestine by activating macrophages and amplifying local inflammatory responses, leading to intestinal permeability and systemic inflammation, which plays a role in autoimmune diseases such as inflammatory bowel disease." (PMID 39609876, 2024).
systemic lupus erythematosus (3 papers, 2022 to 2024). An autoimmune multi-organ disease typically associated with vasculopathy and autoantibody production. "Moreover, DEFA4 has an effective role in autoimmune diseases such as systemic lupus erythematosus (SLE)." (PMID 35668817, 2022). "Villanueva and colleagues showed an enhanced expression of proteins linked to neutrophil antimicrobial activity in systemic lupus erythematosus (SLE) [e.g., myeloperoxidase (MPO), neutrophil elastase (ELANE), alpha defensin 4 (DEFA4)]." (PMID 38596677, 2024).
hearing loss (2 papers, 2025). "This gene is expressed in multiple tissues, particularly epithelial cells, and increased DEFA4 protein expression has been observed in patients with hearing loss." (PMID 41009448, 2025).
acute myeloid leukemia (1 paper, 2022). Acute myeloid leukemia (AML) is a group of neoplasms arising from precursor cells committed to the myeloid cell-line differentiation. "The mRNA expression levels of DEFA1, DEFA3, and DEFA4 in tumor tissues were generally lower than those in normal tissues but significantly higher in tumor cells of acute myeloid leukemia than those in normal tissues." (PMID 36703795, 2022).
adenoma (1 paper, 2025). A neoplasm arising from the epithelium. "We found that DEFA4 is associated with non-advanced adenoma, MPO with advanced adenoma, and CD177 with CRC, suggesting their potential as biomarkers for distinct ACS stages." (PMID 40003985, 2025). "Notably, IFI27 was linked to the symptomatic non-disease control group, DEFA4 to the non-advanced adenoma group, MPO to the advanced adenoma group, and CD177 to the colorectal cancer group." (PMID 40003985, 2025).
Allergy (1 paper, 2015). An allergy is an immune response or reaction to substances that are usually not harmful. "We found that the levels of expression of genes involved in allergy development and innate immunity, including those encoding CLC, MS4A3, DEFA3, DEFA4, IL8RA, and IL8RB, were lower in PBMCs from IgG4-RD patients than from healthy controls." (PMID 25973893, 2015). "The expression of genes related to allergy or innate immunity, including CLC, MS4A3, DEFA3, DEFA4, IL8RA and IL8RB, was lower in PBMCs from patients with IgG4-RD than from healthy controls." (PMID 25973893, 2015).
Alzheimer disease (1 paper, 2022). A progressive, neurodegenerative disease characterized by loss of function and death of nerve cells in several areas of the brain leading to loss of cognitive function such as memory and language. "Furthermore, altered DEFA4 gene expression was found in different neurodegenerative diseases such as Alzheimer's disease (AD) and Parkinson's disease (PD)." (PMID 35668817, 2022).
bacterial sepsis (1 paper, 2019). "Further, Defa4 possesses anti-inflammatory activity on human blood leukocytes and human THP-1 monocytic cells in vitro and can ameliorate bacterial sepsis in vivo (personal communication from A. Ouellette)." (PMID 30807587, 2019).
colitis (1 paper, 2018). Inflammation of the colon. "EtOH feeding caused dramatic reduction of colitis-induced expression of Defa4, Defa5 and Defa6 genes." (PMID 30389960, 2018). "Interestingly, HD5 feeding caused a partial prevention of EtOH effect on colitis-induced expression of Defa4, Defa5 and Defa6 genes in colon." (PMID 30389960, 2018). "HD5 feeding partially blocked the effect of EtOH and DSS-colitis on Defa5 and Defa6 mRNA, but the effect on the mRNA for Defa4 gene was further reduced." (PMID 30389960, 2018). "The expression of Defa4, Defa5 and Defa6 genes was induced by colitis in the colon and EtOH feeding abolished this effect of colitis." (PMID 30389960, 2018). "Results of our present study show that DSS-induced colitis induces Defa4, Defa5 and Defa6 expression in mouse colon, and that EtOH feeding abrogates the colitis-induced expression of defensins in colon." (PMID 30389960, 2018). "DSS-induced colitis also elevated expression of Defa4 and Defa6 genes in the ileum." (PMID 30389960, 2018). "DSS-induced colitis significantly elevated mRNA for Defa4 and Defa5, but not Defa6 genes in the ileum." (PMID 30389960, 2018).
colorectal adenocarcinoma (1 paper, 2022). The most common type of colorectal carcinoma. "The Oncomine database showed that the fold change of DEFA4 in colorectal adenocarcinoma was 1.105." (PMID 36703795, 2022). "The fold change of DEFA4 in colorectal adenocarcinoma was 1.105 (Skrzypczak Colorectal Statistics)." (PMID 36703795, 2022).
colorectal cancer (1 paper, 2025). A primary or metastatic malignant neoplasm that affects the colon or rectum. "Key transcripts, such as MPO, FCGR1A, DEFA4, and CD177, have been highlighted as potential biomarkers of colorectal cancer, underscoring the role of immune dysregulation in tumor development and progression." (PMID 40003985, 2025).
periodontitis (1 paper, 2022). An acute or chronic inflammatory process that affects the tissues that surround and support the teeth. "In oral-related diseases, DEFA4 was observed at low levels among periodontitis patients compared to the healthy subjects, whereas the low expression level of the DEFA4 gene could serve as a potential biomarker to detect periodontal conditions." (PMID 35668817, 2022).
pneumonia (1 paper, 2013). An acute, acute and chronic, or chronic inflammation focally or diffusely affecting the lung parenchyma, caused by an infection in one or both of the lungs (by bacteria, viruses, fungi, or mycoplasma.). "The top 50 over-abundant transcripts in pneumonia were dominated by antimicrobial neutrophil-related genes e.g ELANE, DEFA1B, MMP8, CAMP, DEFA3, DEFA4, MPO, LTF." (PMID 23940611, 2013).
post-traumatic stress disorder (1 paper, 2022). An anxiety disorder precipitated by an experience of intense fear or horror while exposed to a traumatic (especially life-threatening) event. "Recently, DEFA4 was observed to be up-regulated in Japanese women with post-traumatic stress disorder (PTSD) who have elevated levels of IL-6 compared with those who have normal levels of IL-6, suggesting that DEFA4 up-regulation appeared to be correlated with high levels of IL-6." (PMID 35668817, 2022).
staphylococcus aureus infection (1 paper, 2021). An infectious process in which the bacteria Staphylococcus aureus is present. "The second-ranked pathway (though non-significant) was Staphylococcus aureus infection, represented by DEFA4, C3AR1, and HLA-DMB." (PMID 34442377, 2021).
viral pneumonia (1 paper, 2018). Inflammation of the lung parenchyma that is caused by a viral infection. "Among the 87 defensins and associated genes that had expression values available, DEFA4 and DEFA3 were the most significantly differentially expressing defensins between bacterial and viral pneumonia patients." (PMID 30524393, 2018).
infection (5 papers, 2018 to 2024). The state of being infected such as from the introduction of a foreign agent such as serum, vaccine, antigenic substance or organism. "DEFA1 and DEFA4 have been selected to identify the network of genes regulating their expression considering α-defensins as potential novel targets of C. parvum to persist the infection." (PMID 34946170, 2021). "DEFA4 was observed to be more effective than DEFA1, 2, 3 in protecting peripheral blood mononuclear cells (PBMCs) from infection by both strains of HIV-1, although DEFA4 has a significantly weaker capacity in acting as a lectin ligand to gp120 and CD4." (PMID 35668817, 2022). "Furthermore, regarding DEFA4 function in immunity, we cannot completely rule out the impact of infection or the response to drugs that might be responsible for changes in DEFA4 gene expression." (PMID 35668817, 2022).
tumor (5 papers, 2021 to 2025). "DEFA4 encodes a member of defensins thought to be associated with host defense and OLFM4 encodes an anti-apoptotic factor that promotes tumor growth." (PMID 33445803, 2021).
cancer (3 papers, 2022 to 2025). A tumor composed of atypical neoplastic, often pleomorphic cells that invade other tissues. "Head and neck cancers are the most common cancer types that appear to be associated with changes in DEFA4 gene expression levels." (PMID 35668817, 2022). "In this study, we investigated the germline mutation alterations of ADAM6, SIX3, GNAS, NDUFV1, H19, DEFA4, and ZIM2 genes in 82 pediatric cancer patients treated with cisplatin." (PMID 41009448, 2025). "The up-regulation of DEFA4 appears to be involved in the malignant transformation or aggressive form of cancer." (PMID 35668817, 2022). "According to this analysis, DEFA4 has been concluded as one of 48 genes identified as common cancer signature genes." (PMID 35668817, 2022). "Variations in DEFA4 gene expression have been reported in different disorders such as diseases related to inflammation and immunity dysfunction, brain-related disorders, and various cancers." (PMID 36928613, 2023). "On the other hand, alternations in DEFA4 gene expression have been reported in different disorders such as diseases related to inflammation and immunity dysfunction, brain-related disorders, and various cancers." (PMID 35668817, 2022). "Altered DEFA4 gene expression has been observed in bone marrow-related cancers." (PMID 35668817, 2022).
immune diseases (1 paper, 2014). "Since sex hormones, especially estrogen, had immune-modulatory properties and contributed to sex-bias susceptibility to some immune diseases, the effects of estrogen on LTF, CAMP and DEFA4 were also explored in the present study." (PMID 24741625, 2014).
DEFA4 also shares sentences with these, for which no sentence is quoted: idiopathic pulmonary fibrosis (2 papers); infectious disease (2); adenocarcinoma (1); breast carcinoma (1); dengue virus infection (1); inflammatory bowel disease (1); Neonatal sepsis (1); Obesity (1); osteosarcoma (1); Parkinson disease (1); visceral leishmaniasis (1).